FTO (FTO alpha-ketoglutarate dependent dioxygenase)
Diseases named in the same sentence as FTO in open-access papers (continued):
Sharing a sentence is not in itself a finding about the gene and the disease.
breast cancer (174 papers, 2011 to 2026). A primary or metastatic malignant neoplasm involving the breast. "FTO, the pioneering demethylase acknowledged for its recognition of m6A, has been implicated in human diseases, notably breast cancer, by fostering cell proliferation and metastasis, as evidenced in both in vitro and in vivo studies." (PMID 40000966, 2025). "Epidemiological research has indicated that SNPs in FTO are linked to an increased susceptibility to various cancers, including endometrial cancer, breast cancer, pancreatic cancer, and melanoma." (PMID 40391584, 2025). "The fat mass and obesity-associated (FTO) protein, the first RNA m6A demethylase discovered, plays a significant oncogenic role in various cancers 9, notably breast cancer 9-11." (PMID 41281757, 2025). "Studies have shown that single nucleotide polymorphisms (SNPs) in FTO are associated with the risk of various cancers, including breast cancer." (PMID 41269404, 2025). "For instance, research conducted on European and Asian cohorts demonstrates that the AA genotype of the FTO rs9939609 polymorphism is linked to an elevated risk of breast cancer, potentially due to its influence on BMI, hormonal changes, and energy metabolism." (PMID 40630163, 2025). "Remarkably, FTO, an m6A/m6Am RNA demethylase initially identified through its association with obesity, is associated with breast cancer-related SNPs and mechanistically connects metabolic status with cancer susceptibility." (PMID 41373981, 2025). "Analysis revealed that lower expression levels of FTO-BTK/c-Myc were significantly associated with improved OS in breast cancer patients." (PMID 41281757, 2025). "Recent studies have highlighted a significant association between FTO gene polymorphisms, particularly the rs9939609 variant, and breast cancer risk, with findings showing variability across different populations and metabolic contexts." (PMID 40630163, 2025). "For instance, FTO SNPs have been found to be associated with increased risk for breast cancer in multiple ethnic groups." (PMID 40722726, 2025). "On the one hand, FTO was highly expressed in breast cancer and linked with unfavorable survival, advanced TNM stage, and lymph node metastasis." (PMID 40002690, 2025). "Our data identified that fat mass and obesity-associated protein (FTO), an N6-methyladenosine (m6A) demethylase, is highly expressed in breast cancer and promotes tumorigenesis." (PMID 41281757, 2025). "Further data mining of the starBase database for breast cancer (BRCA) samples demonstrated FTO expression negatively associated with ANGPTL4 expression." (PMID 39910592, 2025). "FTO overexpression in breast cancer is implicated in promoting tumor aggressiveness, whereas epitranscriptomic profiling of peripheral blood RNA has identified m6A modifications as novel noninvasive diagnostic biomarkers." (PMID 40986143, 2025). "Down-regulated FTO levels in prostate and breast cancers are associated with prognosis, but the exact mechanism is unclear." (PMID 38384328, 2024). "FTO and PIK3CB demonstrated significant diagnostic performance for breast cancer, with FTO achieving a specificity of 90.63%." (PMID 37861518, 2023). "Senescent neutrophil-derived exosome piRNA-17560 increases binds to fat mass and obesity-associated protein (FTO), reduces its mRNA decay and enhances its stability in breast cancer." (PMID 38031146, 2023). "While in breast cancer high FTO expression levels are associated with increased tumor cell proliferation, increased FTO levels in clear cell renal cell carcinoma resulted in tumor cell growth inhibition." (PMID 35806168, 2022). "FTO was markedly associated with many disease risks, such as leukemia, cardiovascular disease, breast cancer, melanoma, and endometrial cancer." (PMID 35628623, 2022). "Similar to breast cancer FTO abundance is associated in GC with metastasis; marking it as a poor prognostic marker." (PMID 35409166, 2022).
breast cancer (continued). "This comparison revealed that FTO was overexpressed in breast cancer cells; denoting it as a potential diagnostic marker in breast cancer." (PMID 35409166, 2022). "In the previous studies, several FTO single-nucleotide polymorphisms (SNPs) showed an association with breast cancer risk, and FTO is highly expressed in human breast cancer tissues." (PMID 35628623, 2022). "The association between vitamin D and the FTO genotype in patients with breast cancer was assessed after adjustment for cofounders." (PMID 34490746, 2021). "FTO upregulation is significantly associated with shorter overall survival in patients with advanced-stage breast cancer." (PMID 34044876, 2021). "For instance, presence of rs1477196, rs16953002, and TAC haplotype (rs9939609-rs1477196-rs1121980) in the FTO gene is associated with a high risk of breast cancer." (PMID 34094986, 2021). "This study aimed to investigate the association between serum level of 25(OH) vitamin D and FTO genotype in breast cancer patients." (PMID 34490746, 2021). "Contradictory results were reported on the effect of fat mass‐ and obesity‐associated (FTO) gene and anthropometric measurements on breast cancer (BC)." (PMID 33634577, 2021). "FTO, a key m6A demethylase, is up-regulated in human breast cancer and is significantly associated with poor survival rates." (PMID 32754191, 2020). "Their results showed variants of FTO are concerned with varying susceptibility of breast cancer; however, they cannot predict survival outcomes in patients with this disease." (PMID 33292526, 2020). "Decreased m6A methylation by FTO is also associated with breast cancer cell proliferation and metastasis." (PMID 32194861, 2020). "Polymorphisms in FTO are associated with breast cancer, especially estrogen receptor (ER)-positive breast cancer." (PMID 33292526, 2020). "For example, the polymorphisms rs9939609 and rs1477196 in FTO are implicated in an increased risk of breast cancer among women excluding those from Iran." (PMID 33292526, 2020). "Multiple SNPs in the intron 1 region of the FTO (including rs9939609, rs1477196, rs7206790, rs8047395) have been correlated with the risk of breast cancer, with rs1477196 strongly associated." (PMID 33304380, 2020). "It has been found that FTO overexpression was associated with a higher incidence of human breast cancer." (PMID 33511112, 2020). "The most typical FTO SNP rs9939609 was associated with lung cancer, renal cancer, breast cancer, prostate cancer, pancreatic cancer, endometrial cancer." (PMID 33304380, 2020). "High level of FTO was significantly associated with lower survival rates in patients with breast cancer." (PMID 30922314, 2019). "This is in line with previous biological findings, where FTO was shown to be associated with poor prognosis molecular subtypes of breast cancer and AML." (PMID 31069256, 2019). "Further, m6A demethylase FTO has been also found to be overexpressed in breast cancer and associates with a poor survival of breast cancer patients." (PMID 31426393, 2019). "b Measurement of BNIP3 mRNA expression level by overexpression of YTHDF2 in FTO-deficient breast cancer cells." (PMID 30922314, 2019). "FTO is highly expressed and linked with a poor prognosis in breast cancer, but we found that FTO is expressed at low levels in BC." (PMID 31808521, 2019). "For instance, several SNPs of intron 1 of FTO (including rs7206790, rs8047395, rs9939609, and rs1477196) are all significantly associated with breast cancer risk, and rs1477196 shows the strongest association." (PMID 30105001, 2018). "FTO rs9939609 SNP risk allele marginally decreased risk of prostate cancer (OR=0.93, 95%CI=0.88-0.99), while it marginally increased risk of breast cancer (OR=1.12, 95%CI=0.99-1.26)." (PMID 28881622, 2017). "Haplotype analysis showed that FTO TAC haplotype (rs9939609-rs1477196-rs1121980) had significant reduced breast cancer risk (OR = 0.76, 95% CI: 0.62–0.93) compared with TGC haplotype." (PMID 26146447, 2015).
breast cancer (continued). "We genotyped six FTO polymorphisms in a case-control study, including 537 breast cancer cases and 537 controls." (PMID 26146447, 2015). "In this study, we found that two SNPs (rs1477196 and rs16953002) and TAC haplotype (rs9939609-rs1477196-rs1121980) in FTO gene were significantly associated with breast cancer risk." (PMID 26146447, 2015). "To evaluate the ability of the multiple-SNP models of the FTO pathway genotypes to predict breast cancer risk we plotted the receiver operating characteristics (ROC) curve." (PMID 21489227, 2011). "In this clinic-based case-control study we found that SNPs located in intron 1 of FTO are associated with breast cancer risk." (PMID 21489227, 2011). "This indicated that FTO genotypes provided powerful classifiers to predict breast cancer risk and a model with epistatic interactions further improved the prediction accuracy." (PMID 21489227, 2011). "We found that FTO genotypes provided powerful classifiers to predict breast cancer risk and a model with epistatic interactions further improved the prediction accuracy with a receiver operating characteristic (ROC) curves of 0.68." (PMID 21489227, 2011). "We examined the role of single nucleotide polymorphisms (SNPs) of intron 1 of FTO in breast cancer risk." (PMID 21489227, 2011). "Our objective was to evaluate tissue expression of FTO in breast and the role of FTO SNPs in predicting breast cancer risk." (PMID 21489227, 2011). "In conclusion we have shown a significant expression of FTO in malignant and normal breast tissue and that FTO SNPs in intron 1 are significantly associated with breast cancer risk." (PMID 21489227, 2011). "If confirmed in subsequent studies, our findings suggest that genetic variants of FTO alter breast cancer risk." (PMID 21489227, 2011). "The FTO rs9939609 SNP has been linked to higher BMI, insulin resistance, and breast cancer risk." (PMID 42091990, 2026). "Weight loss by bariatric surgery lowers breast cancer risk, particularly in women with baseline hyperinsulinemia, but it is unclear whether this effect varies by FTO genotype." (PMID 42091990, 2026). "Moreover, FTO’s expression correlates with patient outcomes, and its inhibition is linked with reduced tumor growth in breast cancer BrM models." (PMID 40016470, 2025). "In breast cancer, high FTO expression is linked to tumor malignancy and poor patient prognosis." (PMID 41145484, 2025). "Fat mass and obesity associated (FTO) gene and anthropometric measurements might be associated with breast cancer (BC) risk." (PMID 40630163, 2025). "However, the underlying mechanism of FTO as a demethylase in breast cancer progression still needs further investigation." (PMID 38782769, 2024). "Interestingly, the association between FTO gene polymorphisms and breast cancer was reported to be influenced by the status of oestrogen receptors." (PMID 33634577, 2021). "FTO gene polymorphisms may counteract the beneficial effects of vitamin D in breast cancer prevention." (PMID 34490746, 2021). "FTO-induced demethylation of the tumor suppressor BNIP3 mRNA in its 3'UTR causes degradation of the transcript thus eliminating the tumor suppressive effect of BNIP3 in breast cancer." (PMID 32194861, 2020). "It was reported that FTO, a key m6A demethylase, was up-regulated and significantly associated with poor prognosis in breast cancer; FTO-reduced m6A modification could promote breast cancer cell proliferation and metastasis by inhibiting BNIP3 expression." (PMID 32766145, 2020). "However, the underlying epigenetic regulation of FTO, as m6A demethylase, in breast cancer initiation and progression has yet to be investigated." (PMID 30922314, 2019). "It indicates that up-regulation of FTO may be implicated in breast cancer initiation and progression." (PMID 30922314, 2019). "Recent evidence underlines that FTO expression may have a critical role for the risk of breast cancer, especially in HER2-overexpressed breast cancer." (PMID 28933365, 2017).
breast cancer (continued). "FTO is also overexpressed in breast cancer compared to adjacent breast tissues and overexpression is associated with higher metastatic potential and resistance to chemotherapy in an in vitro cellular breast cancer model." (PMID 28672805, 2017). "In addition, FTO rs1477196 SNP was associated with thyroid cancer independently of BMI and FTO rs11075995 SNP was associated with breast cancer dependently on BMI." (PMID 28881622, 2017). "Till now, a number of FTO SNPs, such as rs1477196, rs11075995, rs17817449, rs11075995, and rs1121980, were reported to be associated with breast cancer risk in populations of different ethnic origins, but the results lack consistency and research was rare in Chinese population." (PMID 26146447, 2015). "Two SNPs in FTO gene were significantly associated with risk of breast cancer." (PMID 26146447, 2015). "The aim of this study is to examine whether cancer-related FTO polymorphisms are associated with risk and survival of breast cancer and BMI levels in controls in a Chinese population." (PMID 26146447, 2015). "Furthermore, with an AUC of 0.68 these FTO genotypes provided powerful classifiers to predict breast cancer risk." (PMID 21489227, 2011). "This is to our knowledge the first report of an association between FTO and breast cancer risk." (PMID 21489227, 2011). "Under the epistatic models, all the four FTO SNPs were significantly associated with breast cancer." (PMID 21489227, 2011). "FTO gene risk allele may influence the effect of diet on breast cancer risk." (PMID 36403211, 2022). "The A/A allele was also found associated with reduced expression of FTO, suggesting an epi-transcriptomic mechanism may underlie the dysregulation of genes involved in hormonal biosynthesis leading to an increased risk of breast cancer." (PMID 33785833, 2021). "The only studies of breast cancer have shown that METTL3-mediated enhancement of m6A level could promote the proliferation of breast cancer cells, while the high level of m6A caused by FTO knockdown could inhibit the proliferation and metastasis of breast cancer." (PMID 32766145, 2020). "In the subgroup analysis by cancer type, FTO rs9939609 SNP risk allele marginally increased risk of endometrial cancer (OR=1.07, 95%CI=1.00-1.14) and pancreatic cancer (OR=1.12, 95%CI=1.04-1.21), while it marginally decreased risk of breast cancer (OR=0.94, 95%CI=0.92-0.96)." (PMID 28881622, 2017). "Furthermore, these FTO SNPs are powerful classifiers in predicting breast cancer risk." (PMID 21489227, 2011). "The FTO axis may emerge as an important modifier of breast cancer risk." (PMID 21489227, 2011). "FTO can reduce apoptosis of breast cancer cells and promote their growth by demethylating m6A in the 3′UTR of BNIP3 mRNA and inducing its degradation in a YTHDF2-independent manner." (PMID 40001550, 2025). "Previous studies have also found that STAT3 promoted the transcription of FTO in breast cancer cells." (PMID 40712780, 2025). "In our in vivo studies, the combination of FTO inhibitors with ibrutinib markedly reduced tumor growth and lung metastasis in breast cancer and improved survival." (PMID 41281757, 2025). "FTO has variable effects on tumor growth and prognosis in various malignancies, acting as a carcinogen in cases of breast cancer, cervical cancer, and melanoma." (PMID 40919129, 2025). "Survival analyses indicated that higher FTO expression correlates with lower OS in breast cancer patients, suggesting FTO upregulation worsens clinical outcomes." (PMID 41281757, 2025). "Different from YTHDF2, the high expression of FTO significantly promotes the proliferation, invasion, and migration of breast cancer cells and reduces apoptosis." (PMID 40001550, 2025). "We then analyzed FTO expression using the GSE9014 dataset from the GEO database, which showed that FTO is upregulated in breast cancer tumor tissues compared to normal tissues." (PMID 41281757, 2025).
breast cancer (continued). "FTO inhibitors have been shown to reduce tumor growth in breast cancer BrM models and FTO inhibitor meclofenamate is currently being evaluated as a treatment for BrM (NCT02429570)." (PMID 40016470, 2025). "The knockdown of MIDN suppressed the colony formation of breast cancer cells and upregulated FTO both in breast and gastric cancer." (PMID 40002690, 2025). "Analysis using the TNMplot database revealed pan-cancer upregulation of FTO expression in multiple tumors, including breast cancer." (PMID 41281757, 2025). "We further assess the potential synergistic antitumor effects of combining FTO inhibitors and other clinically approved targeted therapy drugs for breast cancer." (PMID 41281757, 2025). "Together, these data and data from another laboratory show that the m6A‐demethylase FTO promotes proliferation and migration in breast cancer cells." (PMID 40022434, 2025). "In contrast, a study conducted on breast cancer reported a marginally significant reduction (p = 0.05) in FTO gene expression in the breast tissue of patients with the AA homozygous genotype." (PMID 40361322, 2025). "FTO has been reported to exert oncogenic function in various cancers, including melanoma, breast cancer, acute myeloid leukemia, oral squamous cell carcinoma, and so on." (PMID 40712780, 2025). "Once transferred to breast cancer cells, piR-17560 stabilizes FTO mRNA, increasing FTO protein levels and enabling m6A demethylation of ZEB1 mRNA, which prevents its degradation by the m6A reader YTHDF2." (PMID 40805288, 2025). "Further analysis of FTO expression across different stages of breast cancer revealed a progressive increase in FTO expression with disease advancement." (PMID 41281757, 2025). "Research has found that FTO is upregulated in breast cancer and promotes the development of breast cancer." (PMID 40332101, 2025). "To explore the biological roles of FTO in breast cancer malignancy, we introduced shRNA-mediated FTO knockdown (KD) (shFTO#1, #2, and #3) into MDA-MB-231 and BT-549 cells." (PMID 41281757, 2025). "The molecular mechanisms and downstream targets of FTO's function in breast cancer growth and migration remain largely unexplored." (PMID 40022434, 2025). "Results showed that the knockdown of MIDN suppressed the colony formation of breast cancer cells and upregulated the demethylase FTO both in breast and gastric cancer cells." (PMID 40002690, 2025). "In the context of breast cancer, the role of m6A regulatory elements, particularly erasers such as FTO and ALKBH5, in influencing disease advancement remains a subject of debate." (PMID 40016470, 2025). "In a Brazilian cohort of breast cancer patients and controls, the FTO SNPs rs1121980 and rs9939609, in combination with the melanocortin-4 receptor (MC4R) SNP rs17782313, were linked with an increased risk of breast cancer by 4.59-fold." (PMID 40361322, 2025). "In breast cancer, dual inhibition of FTO and the PDK1-AKT signaling pathway using FB23 and BX-912 has been shown to significantly reduce tumor progression." (PMID 41281757, 2025). "Functional studies revealed that FTO promoted breast cancer progression by affecting miR-181b-3p/ARL5B signaling and directly regulating the m6A methylation of 3′UTR of BNIP3 mRNA." (PMID 40002690, 2025). "In breast cancer, FTO mediates m6A demodifications in the 3’UTR of BCL2 interacting protein 3 (BNIP3) mRNA and induces its degradation, promoting breast cancer cell proliferation." (PMID 41373022, 2025). "Inhibiting FTO can suppress the proliferation and metastasis of breast cancer, while its efficacy needs to be further improved." (PMID 41281757, 2025). "For example, METTL3, VIRMA, FTO, and IGF2BP1 aberrant expression linked to breast cancer, METTL3, FTO, and YTHDF1 disrupted expression promotes lung cancer, and METTL3/14, FTO, and YTHDF2 dysregulated expression promotes acute myeloid leukemia." (PMID 38544837, 2024).